BTLA (B and T lymphocyte associated)
Diseases named in the same sentence as BTLA in open-access papers (continued):
Sharing a sentence is not in itself a finding about the gene and the disease.
Sepsis (36 papers, 2013 to 2024). Sepsis is defined as life-threatening organ dysfunction caused by a dysregulated host response to infection. "Expression of HVEM and BTLA have previously been demonstrated to increase lymphocytes in both trauma- and sepsis-induced critical illness, with associated impact on overall septic mortality and changes in nosocomial infection risk." (PMID 37305124, 2023). "Increased BTLA expression on circulating CD4+ T cells in sepsis patients was associated with nosocomial infection." (PMID 36518755, 2022). "In sepsis, soluble BTLA has been associated with disease severity, thus, more studies are needed to understand the impact of this molecule in IBD." (PMID 36558958, 2022). "BTLA expression on CD4+ T-cells also correlates with severity of sepsis in ICU patients and is associated with increased risk of developing nosocomial infections." (PMID 35860251, 2022). "BTLA expression causes apoptotic cell loss in primary and secondary lymphoid organs in mice with experimental sepsis." (PMID 36209190, 2022). "Experimental sepsis models have shown that BTLA deficient mice have a survival benefit, but treating wild type mice with anti-BTLA monoclonal antibody is unfavorable." (PMID 35312715, 2022). "Sepsis mortality is prevented in mice with BTLA deficiency, which presents with reduced leukocyte recruitment into the peritoneum, reduced IL-10 secretion, increased bacterial clearance, and suppressed neutrophil activation." (PMID 33859648, 2021). "Soluble BTLA levels in plasma were higher in the sepsis cohort and is associated with severity of disease." (PMID 34163466, 2021). "Recent studies have implicated a role for BTLA as an important immune checkpoint molecule during sepsis-induced immunosuppression." (PMID 33613563, 2020). "In keeping with our findings, it was shown in an experimental sepsis model that BTLA-deficient mice were protected from kidney injury and had a higher rate of survival." (PMID 28056053, 2017). "Studies have shown that the level of expression of BTLA on circulating T lymphocytes is associated with nosocomial infections and mortality in sepsis." (PMID 26329820, 2015). "Recently, we have also reported that BTLA and PD-1 contribute to septic morbidity and mortality in mice, while also causing innate inflammatory cell dysfunction during acute sepsis." (PMID 24289156, 2013). "In addition, humans with increased leukocyte cell surface expression of BTLA are more likely to have sepsis, are at an increased risk of subsequent infections, and have longer hospital lengths of stay." (PMID 30134817, 2018). "Furthermore, the preceding study also showed that BTLA deficient mice (BTLA−/−) had increased numbers of CD4+ T cells in the spleen following sepsis and implicated a role for BTLA in apoptosis induced T cell loss." (PMID 29135922, 2017). "Furthermore, lower percentage of BTLA+/CD4+ T cells during the early stage of sepsis is associated with the severity and the mortality of septic patients." (PMID 26329820, 2015). "Unlike other co-inhibitory receptors, our results suggested that lower levels of BTLA expression on CD4+ T cells during the early stage of sepsis may increase the risk of pejorative outcome." (PMID 26329820, 2015). "Furthermore, a lower percentage of BTLA+/CD4+ T cells during the early stage of sepsis is associated with the severity of sepsis and the mortality of patients with sepsis." (PMID 26329820, 2015). "Here we find that an increase in the percentage of BTLA+CD4+ T cells is much higher in the patients that develop subsequent nosocomial infections, thus implicating BTLA as a possible biomarker for identifying which critically ill patients are most susceptible to the development of sepsis." (PMID 24289156, 2013). "BTLA is an inhibitory receptor that suppresses immune responses, and its expression might be associated with poor prognosis in tumors, fulminant viral hepatitis, and sepsis." (PMID 38022502, 2023).
Sepsis (continued). "Moreover, genetic variations in BTLA are associated with sepsis morbidity." (PMID 33859648, 2021). "Therefore, in the early stage of sepsis, the percentage of BTLA+/CD4+T cells may contribute to the risk stratification for sepsis." (PMID 26329820, 2015). "We feel that the data presented here concerning BTLA expression on CD4+ T cells in critically ill ICU patients and experimental mice importantly add novel insight as to how ligation of BTLA may contribute to the induction of the adaptive immune cell loss that is associated with sepsis." (PMID 24289156, 2013). "BTLA expression on Tregs remained high in patients with sepsis, compared to healthy controls from day 1 to 7, especially in non-survivors." (PMID 35281010, 2022). "The higher level of BTLA expression also correlated with decreased phagocytosis and bactericidal ability, as well as with the severity of sepsis in these patients." (PMID 35860251, 2022). "In a CLP mouse model of sepsis, BTLA knockout mice had reduced bacterial numbers, reduced organ damage markers, and improved survival." (PMID 36518755, 2022). "As to studies on cell-bound BTLA expression, results are conflicting, ranging from higher to lower CD4+ BTLA expression in sepsis compared to healthy volunteers." (PMID 35312715, 2022). "The BTLA level in Tregs and plasma concentration of sBTLA are elevated in sepsis cases, and they are related to sepsis severity." (PMID 33859648, 2021). "Since severe pulmonary infection is a risk factor for sepsis, this review also summarized the new findings on the role of BTLA in sepsis." (PMID 34163466, 2021). "Previous researches have demonstrated that BTLA plays a role in regulating the immune response in sepsis." (PMID 34163466, 2021). "Higher plasma levels of soluble BTLA (sBTLA) greater than 21 ng/ml, were predictive of five-fold increase in mortality among sepsis patients, implying sBTLA as a prognostic marker during sepsis." (PMID 33613563, 2020). "Increased expression of immune checkpoints including PD-1, PD-L1, 2B4, and BTLA play a major role in sepsis-induced immunosuppression." (PMID 33613563, 2020). "Treatment with anti-BTLA antibody in a two-hit murine model of hemorrhage followed by sepsis lead to increased inflammation, organ injury and mortality." (PMID 33613563, 2020). "This isoform of BTLA has biological significance through changes in cellular proliferation and can predict the diagnosis of sepsis." (PMID 30134817, 2018). "Plasma concentrations of soluble BTLA were increased early in sepsis/septic shock and correlated to severity of disease." (PMID 28056053, 2017). "In CD4+ cells of sepsis survivors, the receptor density of PD-1 appeared to be downregulated, but was upregulated for BTLA." (PMID 27056672, 2016). "The percentages of BTLA+/CD4+T cells were significantly reduced in patients with severe sepsis or septic shock compared with healthy controls." (PMID 26329820, 2015). "Our findings suggest that not only did the percentage of BTLA+/CD4+T cells correlate with the severity of sepsis, but also it was valuable for prognostic evaluation of sepsis." (PMID 26329820, 2015). "Shubin and colleagues also measured the percentage of BTLA+/CD4+T cells in patients with SIRS or sepsis." (PMID 26329820, 2015). "In the early stage of sepsis, there was a stepwise reduction in the percentage of BTLA+/CD4+T cells in patients with SIRS compared with patients with sepsis, severe sepsis, or septic shock." (PMID 26329820, 2015). "Additional studies examining the BTLA expression during both the innate and adaptive immunity will be required to fully understand the roles of BTLA in patients with sepsis." (PMID 26329820, 2015). "In an experimental caecal ligation and puncture mouse sepsis model, including BTLA−/− mice, it was shown that BTLA contributed to the apoptosis of T cells and B cells in the thymus and the spleen, and was associated with peripheral T-cell and B-cell reduction." (PMID 25673430, 2014).
Sepsis (continued). "Upregulation of BTLA on lymphocytes and PD-1 on macrophages is noted to contribute to increased mortality seen in sepsis." (PMID 24796533, 2014). "CD4 + cells in patients with sepsis have an increased expression of inhibitory receptors, including PD-1, 2B4, BTLA, and TRAIL, which could lead to a weakened immune response." (PMID 35910903, 2022). "Sepsis-induced immunosuppression increases the expression of checkpoint inhibitor molecules, such as programmed death protein (PD-1), programmed death ligand 1 (PD-L1), B and T lymphocyte attenuator (BTLA), T cell membrane protein-3 (TIM-3), LAG3, etc.." (PMID 36010357, 2022). "Specifically, relative to that in normal subjects, the number of BTLA+CD4+ T cells decreased among patients with severe sepsis, and a lower percentage of BTLA+CD4+ T cells during the early stage of sepsis was associated with the severity and mortality of sepsis patients." (PMID 33859648, 2021). "At the early stage of sepsis, which is the proinflammatory stage, the expression of BTLA may increase along with the enhanced inflammatory reaction, so as to protect organs from inflammatory storm." (PMID 34163466, 2021). "◾ Increased BTLA correlates with sepsis severity in patients.◾ BTLA-/- mice show reduced mortality." (PMID 33859648, 2021). "Considering that increased expression of inhibitory molecules BTLA and PD-1 on monocytes/macrophages following sepsis has been shown to impact bacterial clearance, these findings suggest that alterations in monocytes/macrophages contribute to defective host innate immunity resulting from sepsis." (PMID 32733454, 2020). "In addition, BTLA was also found to promote the development and progression of sepsis through inhibition of the innate immune response." (PMID 30984188, 2019). "Besides higher expression of BTLA in sepsis, Shubin and co-workers reported a higher proportion of CD4+ T cells expressing BTLA in patients who subsequently developed a nosocomial infection." (PMID 28056053, 2017). "This study showed that 2B4 levels are significantly upregulated on T lymphocytes in both animal model of CLP induced sepsis and human sepsis patients as early as 24 h after sepsis induction, along with an increased expression of other T cell exhaustion markers including PD-1 and BTLA." (PMID 29135922, 2017). "To examine their participation in immune regulation, we aimed to measure plasma concentrations of the soluble isoforms of PD-1, CTLA-4 and BTLA in critically ill patients and evaluate their usefulness as sepsis biomarkers and indicators of severity of disease and prognosis." (PMID 28056053, 2017). "Therefore, the percentage of BTLA+/CD4+T cells was a predictor of pejorative outcome in patients with sepsis as well." (PMID 26329820, 2015). "Interestingly, we observed that the percentage of BTLA+/CD4+T cells was significantly reduced in patients with severe sepsis or septic shock compared with healthy controls (all P <0.01)." (PMID 26329820, 2015). "In contrast to other inhibitory molecules, the changes in BTLA expression during the early stage of sepsis may be more useful for evaluating the prognosis of patients with sepsis." (PMID 26329820, 2015). "However, scarce data are available on BTLA expression in patients with sepsis and further studies are required for understanding the molecular mechanisms." (PMID 26329820, 2015). "Collectively, these studies suggested that high levels of BTLA expression may play a protective role during the early stage of sepsis." (PMID 26329820, 2015). "Similarly, BTLA expression is enhanced in patients with SIRS or sepsis and, in a murine model of sepsis, BTLA-deficient mice displayed an enhanced resistance." (PMID 24886820, 2014). "Accordingly, the exact role of BTLA needs to be further deciphered before strategies targeting BTLA could be proposed to treat patients with sepsis." (PMID 24886820, 2014).
Sepsis (continued). "We therefore set out to understand whether BTLA plays a role in driving lymphocyte dysfunction and apoptosis during sepsis." (PMID 24289156, 2013). "We have previously shown that soluble BTLA (sBTLA) is associated with disease severity and short-term mortality, in severe sepsis and septic shock in the intensive care unit (ICU) setting, and others have further demonstrated that sBTLA can discriminate sepsis from other critical illness." (PMID 35312715, 2022). "The expression of BTLA at different stage of sepsis may have different clinical effects." (PMID 34163466, 2021). "Notably, a growing body of research suggests that BTLA plays an important role in sepsis." (PMID 33859648, 2021). "Pharmacologic blockade of T cell coinhibitory pathways such as PD-1, BTLA, and 2B4 has been shown to at least partially reverse the state of immune dysregulation and improve survival in pre-clinical models of sepsis and PD-1 blockers are currently under investigation for use in clinical sepsis." (PMID 29232699, 2017). "Therefore, low BTLA expression during the first stage of sepsis may result in an over-zealous proinflammatory response which might be as detrimental as high expression at latter stages." (PMID 26329820, 2015). "Based on these results, and the results from our previous study whereby we found that BTLA gene-deficient mice were protected from experimental septic morbidity and mortality, we evaluated the effects of BTLA on CD4+ T cells following experimental sepsis induction in mice." (PMID 24289156, 2013). "Finally, studies that adoptively transfer BTLA-/- CD4+ T cells into WT mice may be able to elucidate whether BTLA expression on CD4+ T cells inappropriately drives an exhausted form of CD4+ T cells into circulation during experimental sepsis." (PMID 24289156, 2013). "BTLA expression has been shown to increase in CD4+ lymphocytes, monocytes, and granulocytes of septic ICU patients, with similar HVEM upregulation after sepsis." (PMID 37305124, 2023). "Elevated expression of cytotoxic T lymphocyte antigen-4 (CTLA-4) on T cells and of B and T lymphocyte attenuator (BTLA) and its binding partner herpesvirus entry mediator (HVEM) on lymphoid and myeloid cells in sepsis has been reported." (PMID 38187375, 2023). "Some research has observed that soluble BTLA and TIM-3, like PD-1 and CTLA-4, is elevated in sepsis patients." (PMID 35958579, 2022). "Furthermore, BTLA may be a valuable biomarker for monitoring the development of sepsis." (PMID 36209190, 2022). "Therefore, targeting BTLA could serve to activate both innate and adaptive immunity during sepsis." (PMID 33613563, 2020). "While increased PD-1 expression on T cells is an established marker of immunoparalysis in sepsis, the roles of CTLA-4 and BTLA remain to be determined." (PMID 28056053, 2017). "Furthermore, there have been no studies exploring whether BTLA expression on circulating CD4+ T lymphocytes is associated with the mortality of patients with sepsis." (PMID 26329820, 2015). "We also examined the correlation between the level of BTLA expression on circulating CD4+ T lymphocytes and the disease severity and mortality of patients with sepsis." (PMID 26329820, 2015). "Our results showed that the percentage of BTLA+/CD4+ T cells was high expression in healthy volunteers and it was statistically reduced in severe sepsis and septic shock compared with healthy controls(all P<0.01)." (PMID 26329820, 2015). "There was a stepwise reduction in the percentage of BTLA+/CD4+T cells within 24 h of ED admission in patients with SIRS compared with patients with sepsis, severe sepsis, or septic shock (P <0.01)." (PMID 26329820, 2015). "As with the human subject observational study above, we evaluated changes in the level of BTLA expression on CD4+ T cells, as well as B cells, following experimental sepsis induction in mice (CLP) as compared with a sham procedure." (PMID 24289156, 2013).
Sepsis (continued). "To determine whether BTLA knockout improves the prognosis of ACLF mice or reduces the bacterial burden, we further constructed a sepsis model via cecal ligation and puncture (CLP) based on ConA-induced ACLF model." (PMID 38418488, 2024). "Besides cancer immunotherapy, it is worth mentioning that BTLA/HVEM axis is also likely to emerge as a critical player in other diseases, including sepsis, neuroinflammation, infectious and autoimmune diseases." (PMID 37649037, 2023). "However, there are conflicting reports on the level of BTLA expression on CD4+ T cells in healthy controls and patients with sepsis." (PMID 26329820, 2015). "A study by Shubin and colleagues showed that increased BTLA+CD4+ lymphocytes were found in patients who developed a subsequent infection, and that BTLA may be a potential biomarker and mediator of sepsis-induced immunosuppression." (PMID 26329820, 2015). "We explore BTLA expression on CD4+ T cells in healthy controls and septic patients, and assess the correlation of BTLA expression on CD4+ T cells in the early stage of sepsis with the severity and mortality of septic patients in the emergency department (ED)." (PMID 26329820, 2015). "Additionally, other studies have found that BTLA contributes to CD4+ T-cell apoptosis in mice; we therefore assessed the contribution of BTLA in lymphocyte apoptosis in our model of sepsis." (PMID 24289156, 2013). "Lack of the gene for BTLA has been shown to improve mortality in animal models of sepsis." (PMID 30134817, 2018). "Additionally, the percentage of BTLA+/CD4+T cells was lower in non-survivors than in survivors, and it was associated with 28-day mortality in patients with sepsis." (PMID 26329820, 2015). "Although we properly compared these ICU patients based on whether they were SIRS or septic, sampling at specific times following ICU admission and septic insult would provide more specific information about the timing of changes in BTLA expression on CD4+ T cells during SIRS and sepsis." (PMID 24289156, 2013). "Although BTLA expression on CD4+ T cells and B cells has been well documented, and expression on these cells has been shown to contribute to a number of disease states, the significance of BTLA expression on lymphocytes during sepsis has yet to be fully addressed." (PMID 24289156, 2013). "• Lack of BTLA protected primary and secondary lymphoid organs from cellular apoptosis, and this was associated with the loss of CD4+ T cells and B cells following CLP in mice, suggesting that BTLA may be directly involved in CD4+ T-cell apoptosis during experimental sepsis." (PMID 24289156, 2013). "Unlike BTLA and TIM-3, plasma levels of soluble CD27 are typically used as a marker of immune activation and currently has not been studied for its role in infection (i.e., sepsis) or burn injuries." (PMID 35958579, 2022). "Additionally, the relationship between the level of BTLA expression on circulating CD4+ T lymphocytes and the severity of sepsis has not been elucidated." (PMID 26329820, 2015).